DKK1 (dickkopf Wnt signaling pathway inhibitor 1)
Diseases named in the same sentence as DKK1 in open-access papers (continued):
Sharing a sentence is not in itself a finding about the gene and the disease.
cancer (continued). "First, while DKK1 expressed by cancer cells inhibits lung metastasis, it promotes bone metastasis due to the respective non-canonical and canonical WNT signaling in these two organs (Zhuanget al., 2017)." (PMID 33824914, 2021). "As a negative regulator of oncogenic Wnt signaling, DKK1 has been shown to inhibit the growth of various cancer cell lines in vitro and in vivo, and DKK1 expression is restrained in some types of cancers due to DNA methylation, polycomb, and micro RNA." (PMID 34117362, 2021). "Collectively, DKK1 is a potential predictor for the prognosis of a wide range of human cancers, along with a positive correlation with β-catenin expression." (PMID 34093545, 2021). "Although a dual role in some cancers has been described for DKK-1, its oncogenic function is predominant and supports its inhibition as a therapeutic approach." (PMID 34884726, 2021). "More studies are warranted to unravel the mechanism of DKK1 protein secretion and its existence in cancer." (PMID 34093545, 2021). "For several years, numerous studies have been conducted to explore the role of DKK1 in various cancers and revealed the different roles of DKK1 in different cancer types." (PMID 34899842, 2021). "Taken together, the consistency of the DKK1 RNAscope results with the qPCR, ELISA, RNA-Seq and IHC data across multiple different cancer cell lines indicates that the DKK1 RNAscope assay is highly specific and accurate." (PMID 33972574, 2021). "DKK1 is overexpressed in bone pathologies and many cancers, has now emerged as a potential biomarker of cancer progression and prognosis for several types of malignancies 1, and has been shown to have immunosuppressive effects." (PMID 34803487, 2021). "DKK1, a Wnt/ß-catenin pathway antagonist, has now emerged as an important regulator in a variety of human cancers." (PMID 33969120, 2021). "This review introduces the rapidly growing body of literature revealing the cancer-promoting and immune regulatory activities of DKK1." (PMID 34093545, 2021). "Wnt antagonists have been described as key modulators of Wnt/β-catenin signaling in cancer, with Dickkopf-1 (DKK-1) being the most studied member of the DKK family." (PMID 34884726, 2021). "Among the differentially expressed genes, 5 (DUSP6, SOX9, DKK1, ARRDC3 and CSRNP2) were known to be associated with signaling pathways in cancer or cancer stem cells." (PMID 32231719, 2020). "Among the Wnt signaling inhibitors, DKK-1 has attracted attention, due to its effect on the invasive and metastatic potential of cancer cells." (PMID 32640686, 2020). "Dkk-1 had been widely investigated in various cancers, in which high levels of Dkk-1 were correlated with poor overall survival." (PMID 33384994, 2020). "Among the four members, the role of DKK1 is widely studied, including the progression of different cancers." (PMID 32140709, 2020). "On the basis of the tumorigenic role of DKK1, DKN-01, a DKK1 monoclonal antibody, was developed for cancer therapy." (PMID 33291655, 2020). "The Dkk-1 was identified as a potential effector based on its inhibitory effect on Wnt signaling, a pathway that was always over-activated in cancer." (PMID 33384994, 2020). "Dkk-1 promoted vasculogenic mimicry formation by inducing NSCLC cells to acquire cancer stem-like cell characteristics." (PMID 33384994, 2020). "Dickkopf-1 (DKK-1) is a secreted protein, and the expression and DKK-1 is different in various cancers." (PMID 32286381, 2020). "In different types of cancers, the up-regulation of DKK1 has been positively correlated with the progression of cancers." (PMID 32140709, 2020). "Along with it, this increase in the expression of both DKK1 and β-catenin was also correlated to the metastasis of cancer to the hilar lymph nodes." (PMID 32140709, 2020). "For example, DKK1 is prognostic for cancer LUAD, but its expression level even is higher in control (health sample) than in some of LUAD samples." (PMID 32489468, 2020).
cancer (continued). "Our study verified that depleting PTOV1 attenuated cancer stem cell traits through impairing DKK1/β-catenin signaling to enhance chemosensitivity of NSCLC cells." (PMID 31387622, 2019). "Abnormal expression of DKK1 has now emerged as an important regulator in a variety of human cancers." (PMID 31285694, 2019). "In a recent study, knockdown of DKK1 in endometrial Ishikawa cancer cells led to enhanced proliferation, migration and invasion." (PMID 31357971, 2019). "Further, studies have shown an immunomodulation role of Dkk-1 in cancer immune surveillance or promoting pathological chronic type 2 inflammation." (PMID 31921182, 2019). "While sclerostin is almost exclusively expressed in osteocytes, DKK1 is secreted by a variety of different cells and tissues including cancer cells." (PMID 30227689, 2018). "Evaluating the contribution of osteocyte-specific markers – FGF23, sclerostin, Dkk-1 – is important, as these proteins have gained attention as potential targets in cancer treatments." (PMID 30568232, 2018). "The rationale for these studies derives from the potential role of DKK-1 as promoter of osteolytic bone lesions through the inhibition of osteoblast functions and, therefore, as a potential adverse marker in multiple cancers." (PMID 30420710, 2018). "Based on our data, we advise caution for the use of DKK1 blood levels as an indicator of the course or prognosis of cancer or chronic diseases in patients." (PMID 30028084, 2018). "Serum DKK1 concentrations were found to be higher in patients with PC, even in early stages, than in cancer-free individuals, and proved more accurate than CA19-9 for PC diagnosis." (PMID 29662668, 2018). "D'Amico L, Mahajan S. Dickkopf-related protein 1 (Dkk1) regulates the accumulation and function of myeloid derived suppressor cells in cancer." (PMID 30400822, 2018). "DKK1 and sFRP are some of the negative regulators of the Wnt/β-catenin targets, which suppress cancer cell proliferation." (PMID 29966001, 2018). "Previous studies have found that CBX7 positively regulates DKK1 transcription via enhancing histone acetylation in breast the cancer cell line MCF7." (PMID 28388562, 2017). "Accumulating evidence indicates that higher serum levels of DKK1 are correlated with poor prognosis of various types of cancer." (PMID 28178355, 2017). "Most importantly, our results established DKK1, a negative regulator of Wnt signaling, as a direct functional effector of miR-373-3p in TSCC, which is in agreement with many studies showing that DKK1 is downregulated in various cancers." (PMID 28337453, 2017). "The expression of many genes that induce adhesion, such as CXCR4 and DCN, and cellular movement in cancer, such as DKK1 and ITGB4, evidently increased when FLRT2 was downregulated, and decreased when FLRT2 was upregulated." (PMID 28325946, 2017). "It has been reported that Wnt signaling inhibition by DKK1 limits the invasiveness of various types of cancer and that pathway activation by lithium chloride normally promotes cancer cell metastasis." (PMID 28337453, 2017). "It has been described for a human cancer that nitric oxide (NO) indirectly upregulates WNT/β-catenin signaling by inhibiting DKK1." (PMID 29165387, 2017). "It was recently shown that IL1β induced NO production in cancer cells was responsible for a strong decrease in DKK1 expression, which in turn resulted in the upregulation of WNT/β-catenin signaling." (PMID 29165387, 2017). "Leap Therapeutics is also using their DKK1 neutralizing antibody to treat several other cancers, but the functional role of DKK1 in these cancers is much less clear." (PMID 27598201, 2016). "Recently, an increased DKK1 serum level has been reported to be useful as a cancer biomarker in lung, esophageal, cervical, and endometrial cancers." (PMID 26799283, 2016). "Beyond its potential use as a biomarker for several diseases, including cancers, DKK1 is viewed by some as a promising target for cancer therapy." (PMID 27367730, 2016).
cancer (continued). "BMI-1 knockout was shown to upregulate DKK1 and to target cancer cells via subsequent downregulation of MYC and CCND1." (PMID 26935956, 2016). "The majority of cancer patients presented elevated DKK1 levels compared to healthy controls and thus confirmed previous data supporting the usefulness of DKK1 as a serological biomarker of cancer." (PMID 27367730, 2016). "DKK1 had been reported to be highly expressed in several cancers and negatively correlated with prognosis." (PMID 26799283, 2016). "Our finding further confirmed the presence of DKK‐1 autoantibody in cancer patients and particular relevance of autoantibodies as biomarkers for early detection." (PMID 26988995, 2016). "For instance, some have highlighted a role of DKK1 in cancer growth through upregulation of stress response genes, such as the Aldehyde dehydrogenase 1A1, which is involved in detoxification of chemotherapeutic agents." (PMID 27367730, 2016). "The DKK1 protein has lately become a focus of attention in cancer research, both as a biomarker and potential therapeutic target." (PMID 27367730, 2016). "This led to an interest in studying DKK1 expression and protein levels in patients with cancers known to induce osteolytic lesions." (PMID 27367730, 2016). "The most highly investigated (and contentious) effect of a Wnt signaling inhibitor on cancer invasion/metastatic potential is by the receptor-binding protein, DKK1." (PMID 26545120, 2015). "Treatment of PC3 cells with DKK1 increased their invasion into the matrigel, correlating high levels of DKK1 expression with a poor cancer prognosis." (PMID 26545120, 2015). "The different expression level of Dickkopf-1 (DKK-1) in different cancers shows that the function of DKK-1 depends on the histological type of the cancer cells and the tissue microenvironment." (PMID 25116444, 2014). "We tested this by treating cancer cells with actinomycin D, a general inhibitor of transcription, and measuring DKK1 mRNA levels in the following hours." (PMID 24898756, 2014). "More importantly, prior studies have demonstrated that exogenous expression of DKK1 increased the migration/invasion activity of mammalian cells, suggesting a significant role for DKK1 in progression of human cancer." (PMID 25144498, 2014). "For example, activation of canonical Wnt/ß-Catenin pathway which is implicated in almost all types of cancers, has often been attributed to epigenetic silencing of Wnt inhibitors like SFRP2 and DKK1." (PMID 24947038, 2014). "Because of the significance of DKK1 in our results and because DKK1 has already been shown to be prognostic for the outcome of a number of malignant tumor entities we focused on this molecule in immunohistochemical validation." (PMID 25048826, 2014). "DKK1 functions as an important inhibitor of the pathway and represents a promising target for cancer therapy." (PMID 24137406, 2013). "Epigenetic regulation through histone modification or DNA methylation was also shown previously for other antagonists of Wnt signaling such as DACT3, sFRPs, WIF1 and DKK-1 in different cancer cells." (PMID 23658527, 2013). "Among 10 cases of NSCLC, 7 showed significantly upregulated expression of DKK1 mRNA in cancer tissue compared with corresponding normal tissue." (PMID 24391982, 2013). "Immunohistochemistry and immunofluoresence revealed that DKK1 was mainly distributed in the cytoplasm in both carcinoma tissues and cell lines." (PMID 24391982, 2013). "As a repressor of cancer cell growth, DKK1 is a main antagonist that interferes with the WNT pathway and downregulates the expression of the downstream target genes including Cyclin D1." (PMID 22815877, 2012).
cancer (continued). "In the present study, we investigated the anticancer properties of genistein by identifying its effects on cancer cell physiology and examining the mechanistic basis of DKK1 activation." (PMID 22815877, 2012). "We found that elevated expression of DKK-1 increased the sensitivity of SHG44 cells to the anti-cancer drug BCNU in vitro." (PMID 20920327, 2010). "The link between DKK1 and Wnt in the context of cancer progression is plausible and currently under investigation." (PMID 17245340, 2007). "This review provides a comprehensive bench-to-bedside overview of DKK1 in cancer." (PMID 42122171, 2026). "Overexpression of DKK1 in cancer cells promotes cell migration, proliferation, and invasion." (PMID 40922300, 2025). "The discovery of antibodies targeting DKK1 is a potential strategy for cancer immunotherapy." (PMID 40394415, 2025). "Furthermore, DKK1 expression is positively correlated with the accumulation of myeloid-derived suppressor cells (MDSCs) in cancer." (PMID 39795613, 2025). "DKK1 has also been studied as a potential target of anti-cancer therapy." (PMID 39795613, 2025). "Therefore, further research incorporating immune cells using allograft or humanized mouse models would be necessary to fully establish DKK1’s roles in cancer patients." (PMID 40025612, 2025). "Indeed, all the genes were overexpressed in the CRC mutant compared to the KRAS WT cancer cell lines, except for DKK1 and ECM1." (PMID 40013338, 2025). "The finding that FGR’s influence on DKK1 is mediated through a signaling pathway involving SP1 highlights the intricate regulatory processes that dictate cancer cell behavior and identifies the FGR-PI3K-AKT-SP1 pathway as a valuable target for therapeutic intervention." (PMID 39788945, 2025). "Notably, CKAP4 interaction with oncogenic ligands, such as DKK1, regulates signaling pathways involved in cancer." (PMID 41149482, 2025). "In addition, the inhibitory effect of DKK1 on Wnt signaling makes it a potential therapeutic target for various diseases, including cancer." (PMID 40943055, 2025). "Increased DKK1 levels have been reported in different types of cancers." (PMID 40922300, 2025). "DKK1 is expressed in cancer epithelial cells in TNBC and HER2+ tumors, in CAFs, and in the bone." (PMID 39885132, 2025). "Although elevated DKK1 levels were linked to poor prognosis, DKK1 did not directly affect cancer cell proliferation." (PMID 40025612, 2025). "Using Depamp analysis data, we compared DKK1 expression across various cancer cell lines." (PMID 40025612, 2025). "In addition, cancer cells via DKK1 acquire stem cell-like functions by preventing Wnt activation regardless of β-catenin dependence." (PMID 40943055, 2025). "DKK1 is tumorigenic in multiple cancer types and immunosuppressive in NK cells." (PMID 40394415, 2025). "Consequently, DKK1 has become a promising target for cancer immunotherapy, and the mechanisms by which DKK1 affects cancer and immune cells have received considerable attention." (PMID 40394415, 2025). "Dickkopf-1 (DKK1) is a secreted protein may promote chemotherapy resistance by inhibiting cancer cell migration and invasion via the Wnt/β-catenin signaling pathway." (PMID 41279138, 2025). "Many investigators confirm that DKK1 is an ideal anti-cancer therapeutic target." (PMID 40943055, 2025). "However, DKK1 blockade showed significant anticancer effects in gefitinib-resistant tumors containing lung fibroblasts, suggesting that DKK1’s pro-tumorigenic roles are mediated through cancer cell-fibroblast interactions." (PMID 40025612, 2025). "Moreover, DKK1‐overexpressing cancer cells promoted cancer cells invasion of peripheral nerves in vitro and in vivo." (PMID 38525111, 2024). "All these results indicated that DKK1 could not only promote cancer cell proliferation and migration abilities but also may induce PNI." (PMID 38525111, 2024).
cancer (continued). "In addition, our study also found that cancer cells overexpressing DKK1 were more invasive toward DRG and induced more neuritogenesis." (PMID 38525111, 2024). "Our study further found that overexpressed DKK1 could enhance the proliferation and migration abilities of cancer cells in vitro and in vivo." (PMID 38525111, 2024). "Although previous studies have postulated cross-regulation between MAPKs and DKK1 in cancer and T cells, it remains largely unknown whether crosstalk exists between the MAPK and Nrf2/DKK1 pathways in human MSCs." (PMID 38529014, 2024). "Among these DEGs, DKK1 emerged as a crucial factor secreted by cancer stem cells." (PMID 39505867, 2024). "DKK1/CKAP4 signaling through PI3K/AKT pathway to promote cancer cell proliferation." (PMID 39107271, 2024). "DKK1 overexpression enhanced the migration abilities of cancer cells." (PMID 38525111, 2024). "Thus, the transient overexpression of DKK1 as an intervention strategy should be viewed with caution in patients with such cancers." (PMID 38529014, 2024). "As shown, overexpressing DKK1 cancer cells induced more neuritogenesis than control cells." (PMID 38525111, 2024). "BASP1, FAP, INHBA, and ITGA5 had been reported to be upregulated in several cancers and could regulate neuronal activity, but their relationship with DKK1, nerves, and HNSCC still remains unknown." (PMID 38525111, 2024). "HE staining showed that nerves were invaded by cancer cells in the DKK1‐overexpressing group." (PMID 38525111, 2024). "DKK1, CTSB, CTSD, and CAPG are also associated with the metastatic potential of cancer." (PMID 37439806, 2024). "As a novel target for cancer therapy, our study supports a role for DKK1 in treating AS further; thus, this may achieve the therapeutic purpose of "killing two birds with one stone" by simultaneously targeting tumors and inhibiting vascular lesions." (PMID 38904030, 2024). "Transwell assays showed that overexpressing DKK1 in cancer cells could promote the migration of SH‐SY5Y cells." (PMID 38525111, 2024). "Dkk1 has been reported as a potential oncogene in a variety of cancers and could be a biomarker for targeted therapy." (PMID 38254908, 2024). "Inhibitors or antibodies against DKK1 may help to enhance the antitumor activity of immune cells, thus providing a novel strategy for cancer treatment." (PMID 37835450, 2023). "DKK1 is a secretory antagonist of the classical Wnt signalling pathway; studies have indicated that dysregulation of the Wnt signalling pathway, induced via the activity of DKK1, is important to cancer cell migration and bone metastasis in lung, breast and prostate cancer." (PMID 38036593, 2023). "On the other hand, the hypermethylation of DKK1 has also been identified as a prognostic factor in cancer patients, indicating that the hypermethylation of this gene in CTCs could have clinical implications as a prognostic biomarker." (PMID 37717096, 2023). "CAF-secreted DKK-1 is a key factor in the promotion of cancer cell dormancy." (PMID 37173977, 2023). "The dysregulation of DKK1 gene is a favorable condition for cancer cells to survive and invade." (PMID 36447119, 2023). "Mechanisms of the cancer-promoting effect of DKK-1 vary based on the cancer context." (PMID 38067123, 2023). "In addition, DKK-1 attenuated the osteoblastic activity of Probasco cells, and bone metastases had decreased cancer-induced intramedullary woven bone formation." (PMID 38067123, 2023). "In addition, DKK1 stimulates cancer advancement through activating the β-catenin-independent Wnt signaling pathway." (PMID 37906341, 2023). "DKN-01 is a humanized antibody that binds to DKK1, inhibiting cancer progression." (PMID 37190019, 2023). "Abnormal expression of DKK1 gene has been detected in a variety of cancer models." (PMID 36447119, 2023). "Additionally, it imposed a pro-cancer effect in pituitary prolactinoma by obstructing the dickkopf Wnt signaling pathway inhibitor 1 (DKK1)." (PMID 37626035, 2023).